LMBR1L (limb development membrane protein 1 like)
Description:
Plays an essential role in lymphocyte development by negatively regulating the canonical Wnt signaling pathway (By similarity). In association with UBAC2 and E3 ubiquitin-protein ligase AMFR, promotes the ubiquitin-mediated degradation of CTNNB1 and Wnt receptors FZD6 and LRP6 (By similarity). LMBR1L stabilizes the beta-catenin destruction complex that is required for regulating CTNNB1 levels (By similarity). Acts as a LCN1 receptor and can mediate its endocytosis.
Synonyms: LIMR; KIAA1174; FLJ10494
Tractability: Antibody: UniProt places it where antibodies can reach, with high confidence; its Gene Ontology location is reachable by antibodies, with high confidence; UniProt predicts a signal peptide or a membrane-spanning region.
Gene: Protein-coding gene on chromosome 12 (49,097,136 to 49,110,900, reverse strand). Ensembl gene ENSG00000139636.
Subcellular location: Cell membrane; Endoplasmic reticulum membrane
Gene Ontology:
Molecular function: protein binding; transmembrane signaling receptor activity
Biological process: receptor-mediated endocytosis; signal transduction; hematopoietic stem cell differentiation; negative regulation of canonical Wnt signaling pathway; T cell apoptotic process; T cell differentiation; T cell proliferation
Cellular component: endoplasmic reticulum membrane; plasma membrane
Genetic constraint (gnomAD): Loss-of-function variants: 40 observed, 62.15 expected, observed/expected ratio (o/e) 0.64, 90% interval 0.5 to 0.84. The upper end of that interval is the gene's LOEUF score, 0.84, which puts it in group 3 of 6, group 1 being the genes least tolerant of losing a copy. Missense variants: 507 observed, 607.93 expected, observed/expected ratio (o/e) 0.83, 90% interval 0.77 to 0.9. Synonymous variants: 246 observed, 259.37 expected, observed/expected ratio (o/e) 0.95, 90% interval 0.85 to 1.05.
Homologues: Orthologues: chimpanzee LMBR1L (99% identical), macaque LMBR1L (98% identical), dog LMBR1L (97% identical), pig LMBR1L (97% identical), mouse Lmbr1l (96% identical), rat Lmbr1l (96% identical), guinea pig LMBR1L (94% identical), rabbit LMBR1L (82% identical), tropical clawed frog lmbr1l (72% identical), zebrafish lmbr1l (69% identical), Drosophila melanogaster lili (46% identical), Caenorhabditis elegans lmbr-1 (36% identical). Paralogues in human: LMBR1 (59% identical).
Diseases named in the same sentence as LMBR1L in open-access papers:
LMBR1L is named in the same sentence as 4 diseases in open-access papers, as found by Europe PMC text mining. Sharing a sentence is not in itself a finding about the gene and the disease. The quoted sentences say what the papers report.
lymphopenia (1 paper, 2023). Reduction in the number of lymphocytes. "In mice, Lmbr1l null variants lead to aberrant activation of Wnt/β-catenin signaling, which in turn results in excessive T-cell apoptosis and lymphopenia." (PMID 37347778, 2023).
LMBR1L also shares sentences with these, for which no sentence is quoted: atherosclerosis (2 papers); cancer (1); colon cancer (1).